DNASE1L3 (deoxyribonuclease 1L3)
Diseases named in the same sentence as DNASE1L3 in open-access papers (continued):
Sharing a sentence is not in itself a finding about the gene and the disease.
viral infection (1 paper, 2019). "Our data further identified numerous ribonuclease and deoxyribonuclease genes with unknown roles in viral infection such as Dnase1l3, Dclre1c, Rexo1, Dxo, and Mgme1." (PMID 31057555, 2019).
tumor (23 papers, 2016 to 2026). "Together, these observations indicate that Dnase1l3 deficiency alters cytotoxic T cells in dLNs and in the tumor microenvironment." (PMID 37581941, 2023). "Dnase1l3 deficiency promotes tumor progression and impairs activity of cDCs in a syngenic tumor model." (PMID 37581941, 2023). "In humans, DNASE1L3 is downregulated in tumor-infiltrating DCs, and this downregulation is associated with poor patient prognosis and reduced tumor immune cell infiltration in many cancer types." (PMID 37581941, 2023). "In the present study, we demonstrated that DNASE1L3 acted as a tumor suppressor through loss- and gain-of-function assays in vivo and in vitro combined with bioinformatics analysis." (PMID 34975319, 2022). "The results strongly suggest the involvement of both the N-terminal region of H2BE and DNASE1L3 in tumor angiogenesis through regulating senescence-associated secretory phenotype in response to stress." (PMID 33744849, 2021). "In conclusion, DNASE1L3 inhibits tumor angiogenesis via impairing the senescence-associated secretory phenotype in response to DNA damage stress." (PMID 33744849, 2021). "In recent years, studies have reported that overexpression of the DNASE1L3 gene in ovarian cancer cells can degrade the tumor cell genome and cause cell death." (PMID 31977318, 2020). "Our study suggests that CD11bloCD172lo cDC2 in tumors might play important roles for activation of CD4+ and CD8+ cytotoxic T cells, and reduction of those cDCs might be reflected by tumor progression in Dnase1l3-deficient mice." (PMID 37581941, 2023). "Notably, the increased tumor formation and growth in Dnase1l3-deficient mice are associated with impaired antitumor immunity, as evidenced by a substantial reduction of cytotoxic T cells and a unique subset of DCs." (PMID 37581941, 2023). "Importantly, the results showed that downregulated DNASE1L3 protein expression was significantly associated with advanced tumor size, number of tumors and microvascular invasion." (PMID 33744849, 2021). "This suggests that DNASE1L3 may inhibit tumor recurrence and metastasis, but the underlying molecular biological mechanism remains unknown." (PMID 31977318, 2020). "Notably, higher expression levels of genes exclusively expressed in the C14 and C38 B cell types (such as BCL11A and DNASE1L3) were positively associated with favorable prognoses, indicating the tumor-suppressive functions of C14 and C38 cells in the PDAC microenvironment." (PMID 38149248, 2023). "Furthermore, Dnase1l3 deficiency in mice delays tissue recovery after damage, increases chronic inflammation and immune cell dysfunction, impairs antitumor immunity, and enhances tumor progression." (PMID 37581941, 2023). "Furthermore, DNASE1L3 expression was tightly associated with tumor grades of HCC." (PMID 34975319, 2022). "Furthermore, from a series of bioinformatics analysis, we found mRNA level of DNASE1L3 was positively linked to the degree of infiltration of various tumor-infiltrating immune cells, the gene expression levels of potential immune checkpoint molecules, and some m6A methylation regulators in LUAD." (PMID 34868195, 2021). "To better understand the molecular drivers of this progression, we investigated DNASE1L3, a gene with putative tumor-suppressive functions." (PMID 41602546, 2026). "We went beyond these observed associations and provided the first genetic evidence to our knowledge for the tumor-suppressor role of DNASE1L3 using Dnase1l3-KO mice." (PMID 37581941, 2023). "In the dLNs, tumor-bearing Dnase1l3-KO mice had fewer CD8+ T cells and activated GZMB+CD4+ T cells compared with WT mice." (PMID 37581941, 2023). "For example, DNASE1L3 (also named DNase1) is a DNA-degrading enzyme expressed at low levels in high-level glycolytic tumour cells." (PMID 37108242, 2023). "A high expression of DNASE1L3 can induce tumour apoptosis, which is considered a prospective and personalized gene-based therapy for cancer." (PMID 37108242, 2023).
tumor (continued). "In order to study the biological function of DNASE1L3 in vivo, we established a subcutaneous xenograft tumour model and a lung metastasis model in nude mice." (PMID 35748106, 2022). "Western blotting and immunohistochemistry then confirmed that the protein expression of DNASE1L3 in HCC tissues was decreased compared with paired adjacent non-tumor tissues." (PMID 34975319, 2022). "The overexpression of DNASE1L3 intensely suppressed tumor growth and decreased tumor weight of the HCC xenograft." (PMID 34975319, 2022). "Functionally, we found that DNASE1L3 inhibited the proliferation of tumor cells by inducing G0/G1 cell cycle arrest and cell apoptosis in vitro." (PMID 34975319, 2022). "Here, we used a combined approach of metabolomics and proteomics that revealed the inhibitory effect of DNASE1L3 on tumor cells to be closely related to the JAK/STAT and glycolysis pathways." (PMID 34975319, 2022). "We found there was a marked downregulation of DNASE1L3 mRNA levels in tumor tissues in contrast to the corresponding adjacent tissues." (PMID 34975319, 2022). "The mRNA expression levels of DNASE1L3 in multiple types of tumors were lower compared with non-tumor tissues." (PMID 33744849, 2021). "Here, we explored the influence mechanism of DNASE1L3 on tumor angiogenesis under DNA damage stress in vitro and in vivo." (PMID 33744849, 2021). "Therefore, this study revealed that DNASE1L3 expression is a tissue-based indicator of tumor stage and provides deeper insights into its role in LIHC prognosis." (PMID 41602546, 2026). "Restoring DNASE1L3 expression may inhibit tumor progression by stabilizing the hepatic microenvironment, though the mechanistic interplay between DNASE1L3, KCs, and metabolic dysfunction remains poorly understood." (PMID 41458908, 2025). "Additionally, we assessed the function of DNASE1L3 in combination therapy using a mouse liver orthotopic tumor model and clinical samples." (PMID 39479454, 2024). "Given the facts that DNA methylation is known to be abnormal in all forms of cancer and DNASE1L3 is dramatically decreased in tumor tissues, a DNA methylation-nuclease preference-cutting end-size distribution axis would serve as a key regulator of cfDNA fragmentation." (PMID 37953260, 2023). "Taken together, our in silico analyses of transcriptomic data from human tumors suggest that downregulation of DNASE1L3 in cDCs may impair antitumor immunity, which in turn contributes to tumor progression." (PMID 37581941, 2023). "Dnase1l3-KO mice developed significantly larger tumors after 18–21 days, indicating that Dnase1l3 deficiency in host cells, but not tumor cells, enhances tumor growth." (PMID 37581941, 2023). "To test the possibility that DNASE1L3 may function as a tumor suppressor, we decided to leverage a previously generated full-body constitutive Dnase1l3-deficient (KO) mouse strain in several models of CRC." (PMID 37581941, 2023). "These immune defects in Dnase1l3-KO mice and DCs may directly contribute to impaired antitumor immunity, resulting in increased tumor growth and progression." (PMID 37581941, 2023). "Next, we analyzed the differential expression of DNASE1L3 based on ∆Ct values in 5 pairs of samples, and the results showed that there were indeed a difference in DNASE1L3 expression between the tumor group and the paracancerous group, and the difference was statistically significant (P=0.036)." (PMID 34157681, 2021). "Finally, we further established a subcutaneous tumor model to investigate the role of DNASE1L3 in tumor angiogenesis." (PMID 33744849, 2021). "We found that stage (P = 0.050), tumour status (P = 0.001), DNASE1L3 expression (P = 0.042), and INTS8 expression (P = 0.023) were independent risk prognostic factors for OS in HCC patients, although no gene was found to be an independent prognostic factor for DFS (data not shown)." (PMID 27567667, 2016).
tumor (continued). "Moreover, in the AOM/DSS CRC model, Dnase1l3 deficiency exacerbated early-phase inflammation that was associated with diminished type I IFN response, and this further led to reduced T cell accumulation and enhanced tumor formation at the later stage." (PMID 37581941, 2023). "Additionally, DNASE1L3 overexpression suppressed tumor growth in vivo." (PMID 34975319, 2022). "All these results demonstrated that DNASE1L3 might regulate the process of intracellular signal transduction and transmission, which could provide a new direction to the research on the crosstalk between tumor cells." (PMID 34868195, 2021). "Thus, whether DNASE1L3 participates in the accumulation of cytoplasmic DNA which in turn affects the progression of HCC via regulating the tumor microenvironments was elucidated." (PMID 33744849, 2021). "All these results indicated that DNASE1L3 might regulate the process of intracellular signal transduction and transmission, which could provide a new direction to the research on the crosstalk between tumor cells." (PMID 34868195, 2021). "The mRNA expression of six inflammation-related genes (C3, CTNNB1, CYBC1, DNASE1L3, IRAK1, and SERPINE1) is closely related to the overall survival rate, tumor immune infiltration, and clinical stage of HCC patients." (PMID 39055701, 2024). "The analysis of TCGA data showed that, CFHR4, DNASE1L3, and SPP2 were significantly higher in adjacent non-tumor tissues, while TAF6 was upregulated in HCC tissues." (PMID 36248822, 2022). "To further determine the expression pattern of DNASE1L3 in HCC, we examined the mRNA expression level of DNASE1L3 in 125 paired HCC samples and adjacent non-tumor tissue samples by quantitative real-time PCR (RT-qPCR)." (PMID 33744849, 2021). "Meanwhile, the DNASE1L3-dependent DNA fragments also provoke the expression of numerous SASP factors and promote tumor angiogenesis." (PMID 33744849, 2021). "Up-regulated expression of DNASE1L3 relieves cytoplasmic DNA accumulation under DDR activation, in turn cell senescence and SASP were arrested, tumor angiogenesis was impaired." (PMID 33744849, 2021). "The Mann–Whitney U test or Kruskal–Wallis rank sum test method was applied to analyze the correlation between the expression level of DNASE1L3 and age, gender, TNM stage, pathologic stage, residual tumor, and smoking status." (PMID 34868195, 2021). "Also, we identified novel predicted tumor-suppressive ligands (SLIT3, DCN, CCN3, THBS1, INHA and INHBA), proteins (DNASE1L3, SULF1, PTEN, OAS1, and DAB2IP), and receptors (P2RX4, CDHR2, PTPRJ, and PTPRH) in MSC1 cells." (PMID 40564222, 2025). "Notably, DNASE1L3 has been reported to inhibit HCC progression by inducing cell apoptosis and weakening tumor glycolysis." (PMID 37215979, 2023). "The real-time quantitative PCR results showed that CFHR4, SPP2, and DNASE1L3 were expressed higher in non-tumor tissues (Non-Tumor) than in tumor tissues (Tumor), and TAF6 was expressed higher in tumor tissues than in non-tumor tissues." (PMID 36248822, 2022). "Mechanistically, during DNA damage, DNASE1L3 translocates to the nucleus, interacts with H2BE, participates in the degradation of unsuccessful repaired DNA, and relieves tumor cell senescence as well as the expression of SASP factors contributed to the microenvironments." (PMID 33744849, 2021). "Interestingly, expression levels of the proinflammatory genes that were upregulated in the colon of Dnase1l3-KO mice at earlier time points did not significantly differ between the final isolated tumors from the 2 genotypes (tumor)." (PMID 37581941, 2023).
tumor (continued). "The expression of markers of monocytes/macrophages were induced in tumors in both WT and Dnase1l3-deficient mice in the AOM/DSS CRC model, but proinflammatory cytokines produced by those cells were not sufficient to suppress tumor progression in Dnase1l3-KO mice." (PMID 37581941, 2023). "Real-time quantitative PCR results disclosed that MPC1, ZG16, RBM47, CPM and DNASE1L3 were expressed at higher levels in adjacent normal tissues than in tumor tissues, and SMOX expression was higher in tumor tissues than in non-tumor tissues." (PMID 38914961, 2024).
cancer (21 papers, 2019 to 2025). A tumor composed of atypical neoplastic, often pleomorphic cells that invade other tissues. "Our study demonstrates that DNASE1L3 is downregulated in tumors and that this downregulation is associated with poor patient prognosis in many cancer types in humans." (PMID 37581941, 2023). "In several cancers, including BC, the level of DNase1L3 is lower than in normal cells, resulting in fewer DNase1L3-associated end motifs." (PMID 36430675, 2022). "DNASE1L3 is widely down‐regulated in human cancers, and the down‐regulation of DNASE1L3 is associated with poor prognosis in various types of cancers." (PMID 34726341, 2021). "In our study, the mutation status of several cancer-related genes with high mutation probability in LUAD significantly affected the expression of DNASE1L3." (PMID 34868195, 2021). "The normal function of DNASE1L3 may help maintain genomic stability by preventing the accumulation of DNA fragments, which may otherwise lead to mutations and cancer." (PMID 39055701, 2024). "Combining with the fact that DNASE1L3 is generally downregulated across multiple cancers (The Cancer Genome Atlas, TCGA database), inactivation of DNASE1L3 is proposed to be the reason underlying the aberrant cfDNA profile in cancer patients." (PMID 37953260, 2023). "Second, our bioinformatic analysis of cancer patients indicates that DNASE1L3 could be evaluated as a predictive biomarker for risk and prognosis of various human cancers, and this is also supported by 2 recent studies." (PMID 37581941, 2023). "Low expression of DNASE1L3 was considerably associated with cancer vasculature invasion." (PMID 33744849, 2021). "Furthermore, many human cancers exhibit down-regulation of DNASE1L3 expression, and DNASE1L3 deficiency in mice led to delayed tissue recovery, increased chronic inflammation, immune cell dysfunction, impaired antitumor immunity, and ultimately affected the antitumor immune responses." (PMID 38196018, 2024). "This was postulated to be related to a downregulation of expression of DNASE1L3 in cancers, which is a key nuclease for plasma DNA fragmentation." (PMID 41245504, 2025). "For example, PKMYT1 showed “oncogene-like” behavior in 5 cancer types, and DNASE1L3 recurrently showed “suppressor-like” behavior in 5 cancers." (PMID 38807223, 2024). "The expression of LPCAT1, NDRG1, G6PD, CYP7A1, SPP1, SFN, and CDCA8 was significantly higher in cancer tissues than in paraneoplastic tissues, whereas the expression of DNASE1L3 was significantly lower in cancer tissues." (PMID 37717019, 2023). "In our study, the mRNA expression level of DNASE1L3 is lower in the cancer samples than that in normal samples." (PMID 37950156, 2023). "In the human cancer data from the TCGA research network, they observed that the expression levels of DNASE1L3 across multiple cancers were generally downregulated." (PMID 34815523, 2022). "The prominent concordance between distinctive DNASE1L3 expression and cytoplasmic DNA accumulation under DNA damage response observed in HCC cancer cells prompted us to further explore the functional implications of DNASE1L3 in damaged cells." (PMID 33744849, 2021). "In current study, we comprehensively analyzed DNASE1L3 expression data of LUAD patients in TCGA (The Cancer Genome Atlas), GEO (Gene Expression Omnibus), CPTAC dataset, and Human Protein Atlas (HPA) database." (PMID 34868195, 2021). "Conversely, SOCS2 and DNASE1L3 were down‐regulated in most cancer tissues compared to normal tissues." (PMID 34726341, 2021). "In our research, cancer cells defected of DNASE1L3 tend to avoid cell death by surpassing apoptotic processes." (PMID 33744849, 2021). "As another example, DNASE1L3 gene behaves as “suppressor-like” in 5 cancer types." (PMID 38807223, 2024).
cancer (continued). "To evaluate the possible involvement of DNASE1L3 in cancer, we first analyzed RNA-Seq data sets from TCGA and found that the mRNA levels of DNASE1L3 were significantly downregulated in a wide range of human cancer types compared with their adjacent normal tissues." (PMID 37581941, 2023). "Specifically, we show that downregulation of DNASE1L3 in cancer, observed by others and in the present study, stems from specific downregulation of this gene in DCs, the main cell type that physiologically expresses DNASE1L3." (PMID 37581941, 2023). "Herein, we systematically investigated the possible role of DNASE1L3 in mediating the interaction between immune cells and cancer cells in both humans and mice using bioinformatics analyses of The Cancer Genome Atlas (TCGA) data sets and various mouse intestinal/colorectal cancer (CRC) models." (PMID 37581941, 2023). "DNASE1L3 gene expression and functions in carcinoma have been recently reported." (PMID 34868195, 2021).
myopathy (1 paper, 2021). A disease of the muscle in which the muscle fibers do not function properly. "Furthermore, its calcium ion dependency could indicate some relationship between the downregulation of CALM2 and DNASE1L3, narrowing the hypothesis that the dysregulation of calcium signaling is one of the most important pathways contributing to WS myopathy." (PMID 34381378, 2021).
DNASE1L3 also shares sentences with these, for which no sentence is quoted: breast carcinoma (2 papers); vasculitis (2); adenocarcinoma (1); diabetes (1); dyslipidemia (1); fatty liver (1); gastric cancer (1); head and neck cancer (1); head and neck squamous cell carcinoma (1); Hypercholesterolemia (1); infection (1); inflammatory bowel disease (1); inflammatory skin disorder (1); lung carcinoma (1); lupus erythematosus (1); nasopharyngeal carcinoma (1); osteosarcoma (1); Primary immunodeficiency (1); renal carcinoma (1); renal disease (1); rheumatoid arthritis (1); sarcoma (1); scleroderma (1); sphingolipidoses (1); Wolman disease (1).